NPHS1 (NPHS1 adhesion molecule, nephrin)
Diseases named in the same sentence as NPHS1 in open-access papers (continued):
Sharing a sentence is not in itself a finding about the gene and the disease.
glomerular disease (10 papers, 2014 to 2025). "NPHS1 mutation or reduced NEPHRIN expression was found to be involved in various glomerular diseases." (PMID 35203286, 2022). "Collectively, Epb41l5fl/fl*Nphs1-rtTA-3G*tetOCre mice developed typical FSGS-like glomerular disease with hallmark features of severe NS but exhibited only minimal overlapping CKD phenotypes." (PMID 34203913, 2021). "Another type of NS is congenital nephrotic syndrome of the Finnish type (CNF), a glomerular disease caused by mutation of NPHS1 gene that encodes protein nephrin, localized on the slit diaphragm." (PMID 24397250, 2014). "The genes with the highest lifetime risk for monogenic glomerulopathy were COL4A3, followed by COL4A4, CRB2, NPHS1, and NPHS2." (PMID 40677321, 2025). "In addition, given the convenience and efficiency of generating transgenic zebrafish, our new zebrafish model is potentially a useful platform to perform functional studies of disease-causing alleles of NPHS1 identified in human patients of CNF and other glomerular diseases." (PMID 36187478, 2022).
focal segmental glomerulosclerosis (6 papers, 2015 to 2024). A renal disorder characterized by sclerotic lesions in the glomeruli. "Furthermore, compound heterozygous or homozygous NPHS1 mutations have also been identified in families with adults with focal segmental glomerulosclerosis (FSGS)." (PMID 30255020, 2018). "However, all eleven Nphs1-Cre/Dach1fl/fl mice displayed abnormal albuminuria, and seven (63%) of them developed focal segmental glomerulosclerosis." (PMID 38805434, 2024).
renal failure (6 papers, 2009 to 2025). "CNS patients with NPHS1 variants developed kidney failure significantly later than those with the other gene variants (31.0 vs. 1.0 months; P < 0.001)." (PMID 40095038, 2025). "CNS patients with NPHS1 variants developed kidney failure significantly later than those with the other variants." (PMID 40095038, 2025). "In patients with pathogenic variants other than NPHS1, there was a significant difference in the age at developing kidney failure between CNS and infantile NS patients (1.0 vs. 15.0 months; P < 0.001)." (PMID 40095038, 2025). "Based on previous studies, the age of developing kidney failure was compared between CNS patients with NPHS1 and those with the other gene variants." (PMID 40095038, 2025). "The age at developing kidney failure was significantly earlier in CNS patients with genes other than NPHS1 than in CNS patients with NPHS1 variants (1.0 vs. 31.0 months; P < 0.001)." (PMID 40095038, 2025). "Patients with CNS progressed to kidney failure earlier than those with infantile NS regarding NPHS1 variants, as well as when all non-NPHS1 variants were combined (31.0 vs. − months; P = 0.025, and 1.0 vs. 15.0 months; P < 0.001, respectively)." (PMID 40095038, 2025). "For example, mutations affecting NPHS1 (encoding the slit diaphragm protein, nephrin) or NPHS2 (encoding the slit diaphragm-associated protein, podocin), result in renal failure and death within a few days after birth." (PMID 23236390, 2012). "Patients with NPHS1 biallelic severe variants and those with NPHS1 monoallelic severe variants were not significantly different in age at the development of kidney failure (31.0 vs. 25.2 months; P = 0.29)." (PMID 40095038, 2025). "Of patients with NPHS1 variants, no infants with NS had any truncating variants or developed kidney failure during follow-up." (PMID 40095038, 2025). "Renal function remains quite normal for the first months in NPHS1, but in other forms, kidney failure may develop faster." (PMID 17968594, 2009).
Alport syndrome (5 papers, 2015 to 2024). A rare renal disease characterized by glomerular nephropathy with hematuria progressing to end-stage renal disease (ESRD), frequently associated with sensorineural deafness, and occasionally with ocular anomalies. "Seven patients had NPHS1 gene mutations, and 1 (case 6) had both NPHS1 and COL4A5 (the gene that causes Alport syndrome) mutations." (PMID 31456999, 2019). "Notably, patient 6 had both NPHS1 mutations (CNS) and COL4A5 gene mutations (Alport syndrome) along with active CMV infection." (PMID 31456999, 2019).
membranous nephropathy (4 papers, 2014 to 2023). "In these studies, the association of the IL-6, NPHS1 (nephrin), TLR-4, TLR-9, STAT4 (signal transducer and activator of transcription) and MYH (mutY DNA glycosylase), genes with susceptibility to primary membranous nephropathy in Taiwan was established." (PMID 32933213, 2020).
nephrotic syndrome type 1 (4 papers, 2014 to 2025). "Congenital nephrotic syndrome of Finnish type (CNF) is an autosomal recessive disease resulting of mutations in the NPHS1 gene.Patients with nephrotic syndrome die during the first two years of life as the condition advances quickly after birth." (PMID 41466700, 2025). "It is most commonly caused by mutations in the NPHS1 gene associated with nephrotic syndrome type 1, also known as Finnish-type CNS, which is inherited in an autosomal recessive manner." (PMID 33938658, 2021). "NPHS1 and NPHS2, the responsible genes for Finnish-type congenital nephrotic syndrome and autosomal recessive steroid-resistant nephrotic syndrome, respectively, encode nephrin and podocin, both of which are expressed in podocytes." (PMID 25184792, 2014). "Homozygous variant in NPHS1 (MIM#602716), nephrotic syndrome, type 1 (MIM#256300, AR); report not available." (PMID 41477467, 2025).
diabetes (3 papers, 2014 to 2023). "Thus, in addition to diseases caused by mutations in NPHS1, reduction in NPHS1 expression is also closely associated with the development of albuminuria, as observed in experimental models of both diabetes and hypertension." (PMID 25309512, 2014). "We further demonstrated that INV-202 blocked the deleterious effects of diabetes on the expression of the genes (Nphs1, Nphs2, and Pdxl) coding for structural proteins (nephrin, podocin, and podocalyxin, respectively)." (PMID 37675364, 2023). "Expressions of podocyte markers nephrin (Nphs1) and podocin (Nphs2) were decreased by diabetes but elevated to nondiabetic levels in diabetic PPKM2Tg mice." (PMID 35133981, 2022).
Nephropathy (2 papers, 2010 to 2019). A nonspecific term referring to disease or damage of the kidneys. "Finnish nephropathy is also present outside Finland and, in a recent survey of 80 sporadic cases, NPHS1 mutations accounted for 22.5% of nephrotic cases in the first year of life and was second to only NPHS2 as a causal factor of NS." (PMID 19066979, 2010). "Mutations in NPHS1 cause an AR disorder characterized by a congenital NS that is common in Finland; for this reason it is called Finnish nephropathy (FN)." (PMID 19066979, 2010).
amyloidosis (1 paper, 2019). A disorder characterized by the localized or diffuse accumulation of amyloid protein in various anatomic sites. "Given the sentence, "Hsf-1 affects podocyte markers NPHS1, NPHS2 and WT1 in a transgenic mouse model of TTRVal30Met-related amyloidosis," three entity relations, with relation type and biological context, were extracted by the context-based ABC model." (PMID 31017923, 2019).
anencephaly (1 paper, 2009). A rare neural tube defect during pregnancy, resulting in the absence of a large portion of the brain and skull in the fetus. "If the AFP concentration in amniotic fluid is very high and the ultrasound examination does not reveal fetal anencephaly or other malformations, NPHS1 is a probable diagnosis." (PMID 17968594, 2009).
breast carcinoma (1 paper, 2023). "Among the identified genes, three mRNAs, AGBL2, HIST2HAC, and NPHS1, show a significant association with the overall survival of breast cancer patients, with Log-rank test p values of < 0.05." (PMID 38012271, 2023). "Based on our analysis, NPHS1 exhibits significant prognostic value and shows differential expression between normal-like subtype and the other four breast cancer subtypes." (PMID 38012271, 2023).
Denys-Drash syndrome (1 paper, 2021). Denys-Drash syndrome (DDS) is a rare urogenital disorder characterized by the association of diffuse mesangial sclerosis (DMS), male pseudohermaphroditism with a 46,XY karyotype, and nephroblastoma. "A clinical presentation that is suggestive of a particular syndromic form of CNS, such as Denys Drash Syndrome or Pierson Syndrome, or Finnish ethnicity, which is associated with founder pathogenic variants in NPHS1, may lead to direct testing of the suspected causative gene." (PMID 33514942, 2021).
lupus nephritis (1 paper, 2021). Glomerulonephritis in the context of systemic lupus erythematosus. "In agreement with this evidence, the same technique was used to demonstrate the pathogenicity of a NPHS1 gene variant of unknown significance in a patient with refractory lupus nephritis." (PMID 33401654, 2021).
microcephaly (1 paper, 2025). A congenital or acquired developmental disorder in which the circumference of the head is smaller than normal for the person's age and sex. "Of the reported participants with the NPHS1 variant (NM_004646.4:c.106 delG), one had extra renal manifestations, which include microcephaly and pulmonary valve stenosis, while the one with the NPHS2 NM_004646.4:c.781G>T variant presented with pulmonary artery stenosis." (PMID 41300747, 2025).
periodontitis (1 paper, 2024). An acute or chronic inflammatory process that affects the tissues that surround and support the teeth. "In this study, our correlation analysis with dbSNP showed that ILDR1 and NPHS1 were associated with severe periodontitis (P < 0.05)." (PMID 37435641, 2024). "The allele frequencies at the mutation loci of LFNG, LENG8, NPHS1, HFE, ILDR1, and DMXL2 genes were analyzed in the 15 patients with severe periodontitis." (PMID 37435641, 2024). "We found that the allele loci of NPHS1(rs114615449), ILDR1(rs142746163), and DMXL2(rs3078066) showed significant differences between the severe periodontitis patients and dbSNP 155 (East Asian race) (P < 0.05)." (PMID 37435641, 2024).
peritonitis (1 paper, 2022). Inflammation of the peritoneum (tissue that lines the abdominal wall and covers most of the organs in the abdomen). "In patients with NPHS1 mutations, the survival and complication rates (peritonitis, central line infections, septic episodes, thrombotic events, height SDS) were not different in patients who were treated with bilateral nephrectomy and RRT, compared to patients who underwent conservative treatment." (PMID 36210940, 2022).
Sepsis (1 paper, 2022). Sepsis is defined as life-threatening organ dysfunction caused by a dysregulated host response to infection. "In 21 infants with CNS due to pathogenic variants in NPHS1 (frequently called “Finnish type NS”), with a median follow-up of 1.1 years, one study reported 63 verified, and 62 suspected, episodes of sepsis." (PMID 36210940, 2022).
kidney diseases (21 papers, 2010 to 2022). "They include numerous genes associated with kidney diseases, such as Chga/Chgb, Ptprn, Nphs1/Nphs2, Nsf, Rph3a, Podxl and Cyp11a1." (PMID 36130284, 2022). "In this study, data of 30 children with renal disease putatively caused by NPHS1 variants were collected from CCGKDD, which had included the data of 2,297 patients (30/2,297, counting for 1.30%)." (PMID 34859019, 2021). "On the one hand, due to the very low frequency of renal disease resulting from NPHS1 variants, individuals and general clinicians are unfamiliar with the disorder as well as its prognosis." (PMID 34859019, 2021). "We retrospectively collected information regarding the genotype and phenotype of NPHS1-associated kidney disease from the registry and investigated the associations between clinical and genetic findings." (PMID 34859019, 2021). "These mutations have been found in various kidney diseases, however, the relationship between NPHS1 mutation and FSGS was relatively less explored." (PMID 31216994, 2019). "In fact, pathogenic variants in various genes responsible for inherited kidney diseases (patients with NPHS1, EYA1, LAMB2, and CLCN5 gene mutations) were detected by NGS in our study." (PMID 31364286, 2019). "The mutations of NPHS1 gene could lead to the occurrence of different degrees of kidney diseases, however, studies which investigated the relationship between NPHS1 gene mutations and FSGS were limited, especially in China." (PMID 31216994, 2019). "The patient therefore has MIDD, and the renal disease may be aggravated by the NPHS1 variant." (PMID 28012006, 2017). "In 2019, national cohort of children with renal disease from 13 different regions of China were recruited from 2014 to 2018, ADCK4, WT1 and NPHS1 were the top three commonly mutated genes in the SRNS group with mutation rates of 5.7, 5.4, and 2.8%, respectively." (PMID 35755072, 2022). "Some of these genes are known for rare Mendelian kidney disease where now a new common or less-frequent variant is implicated for affecting general kidney function (PKDH1 with new certainty, NPHS1 and HNF1A in novel loci), a phenomenon observed also in other contexts, like MC4R for obesity." (PMID 34272381, 2021). "Similarly, other genes such as nephrin (NPHS1) and podocin (NPHS2) contribute to the loss of renal function during renal diseases." (PMID 21859496, 2011). "Moreover, it is tempting to speculate that carriers of single NPHS1 mutations, as in the case of the father herein with adult-onset IgAN, may be predisposed to kidney diseases that manifest later in life, though we cannot rule out the possibility of undetected mutations in other key podocyte genes." (PMID 30212551, 2018).
infection (4 papers, 2021 to 2022). The state of being infected such as from the introduction of a foreign agent such as serum, vaccine, antigenic substance or organism. "P/LP variations in NPHS1, which encodes nephrin, were detected in seven patients with massive proteinuria, edema, infection, and poor feeding or respiratory distress." (PMID 34733806, 2021). "The increased expression of NPHS1 may result from compensatory mechanism to help maintain podocyte physiology post-infection and minimize destabilization of their cellular phenotype as previously reported in a diabetic model of podocyte injury." (PMID 35517495, 2022). "No significant changes in the levels of expression of podocyte marker genes (WT1, PODXL, NPHS1, NPHS2, and MAFB) or for tubular marker genes (SLC3A1 and SLC16A1) were found after infection comparing WT and ACE2 KO kidney organoids." (PMID 35561674, 2022).
autosomal recessive disease (1 paper, 2014). Autosomal recessive form of disease. "Most cases of CNS are autosomal recessive diseases caused by genetic defects in different components of the glomerular filtration barrier (primary CNS), especially by mutations in nephrin (NPHS1, nephrotic syndrome type 1) and podocin (NPHS2) genes." (PMID 24682440, 2014).
immune disorder (1 paper, 2017). "As regards to the non-syndromic forms, some are related to a still not completely understood underlying immune disorder, while an increasing number is found to be caused by mutations in genes highly expressed in podocytes (e.g. NPHS1, NPHS2, CD2AP, PLCE1, ACTN4, TRPC6, and INF2)." (PMID 28298181, 2017).
NPHS1 also shares sentences with these, for which no sentence is quoted: tumor (17 papers); neurofibroma (8); glomerulopathies (5); neurofibromatosis (4); Parkinson disease (4); nephrosis (3); autosomal dominant polycystic kidney disease (2); autosomal recessive steroid-resistant nephrotic syndrome (2); cancer (2); ciliopathies (2); diabetic nephropathy (2); genetic disease (2); glomerulosclerosis (2); Hypertension (2); Hypoalbuminemia (2); malignant peripheral nerve sheath tumor (2); melanoma (2); minimal change disease (2); schwannoma (2); schwannomatosis (2); Stroke (2); 22q11.2 duplication syndrome (1); Anxiety (1); Bartter syndrome (1); Blepharophimosis (1); chronic kidney disease (1); colorectal cancer (1); cutaneous disorders (1); cystic kidney disease (1); digestive system neoplasm (1).
A further 26 diseases each share a sentence with NPHS1 in 1 paper.